PKD2-DT (PKD2 divergent transcript)
Gene: Long non-coding RNA gene on chromosome 4 (87,996,438 to 88,007,523, reverse strand). Ensembl gene ENSG00000289034.
Gene Ontology:
Molecular function: pre-mRNA 5'-splice site binding
Biological process: mRNA 5'-splice site recognition
Cellular component: U1 snRNP